BCR (BCR activator of RhoGEF and GTPase)
Diseases named in the same sentence as BCR in open-access papers (continued):
Sharing a sentence is not in itself a finding about the gene and the disease.
tumor (continued). "In particular the fraction of cancer cells in blood—that will be referred to as tumor burden from now on—can be reliably estimated by analyzing the expression level of the fusion gene BCR-ABL, thus providing an easy way to monitor the disease progression, as well the response to therapy." (PMID 32548108, 2020). "The effect of ZT55 on tumor cell proliferation was studied in 11 human cell lines of both hematologic and solid tumor origin, including HEL cells (harboring the JAK2V617F mutation), and TF-1 cells (carrying wild-type JAK2 but BCR-ABL-transformed)." (PMID 30717771, 2019). "The major BCR clones in each tumor had distinct CDR3 sequences." (PMID 30125329, 2018). "Moreover, BCR-ABL signaling blockage by p-niclosamide as detected in tumor tissues from these xenografted mice supports the on-target effect of p-niclosamide." (PMID 29358661, 2018). "The CDR3 sequences of BCR clones in each tumor were analyzed as described in the methods." (PMID 30125329, 2018). "The prevalence of non-functional TCR/BCR in ALL (both B and T ALL) again supports the recent hypothesis that the TCR/BCR might play a tumor suppressive role in most precursor ALL." (PMID 30285677, 2018). "Furthermore, a recent study on a BL mouse model suggests that the expression of the BCR is required for the fitness of these tumor cells." (PMID 29669863, 2018). "Using quantitative phosphoproteomics, we identified BCR as a new DDR1 substrate and demonstrated that nilotinib prevents DDR1‐mediated BCR phosphorylation on Tyr177, which is important for maintaining β‐catenin transcriptional activity necessary for tumour cell invasion." (PMID 29438985, 2018). "Alternatively, as noted recently, the pre BCR may function as a tumor suppressor in the majority of precursor B-ALL." (PMID 30285677, 2018). "The potentially tumor-promoting role of PDAC could be outsmarted, particularly if KRAS-directed B cells promote tumor progression upon binding of their BCR to the nominal target antigens and subsequent production of tumorigenic cytokines." (PMID 30283732, 2018). "However, formation of metastasis was blocked by the presence of SOCS1 in the SOCS1/BCR-ABL group supporting a tumor suppressive role for SOCS1." (PMID 28753604, 2017). "Even if the mechanism of expression remains not completely defined, it is worthwhile that MM-released exosomes constitutively express on their surface the immunoglobulin of B-cell receptor (Ig-BCR) derived from the parental tumor B-cell, and thus they can be reliable tumor markers." (PMID 29029605, 2017). "However, CML has unique properties: it is a highly homogeneous tumour with all the cells carrying the same BCR/ABL molecular defect and the tumour cells are addicted to the activity of this oncogene." (PMID 28690678, 2017). "However, as we have reviewed here, BCR-ABL has the ability to functionally inactivate several tumor suppressors allowing to promote tumorigenesis through an highly complex signal transduction network." (PMID 27184141, 2016). "Notably, miR-203 has been well documented as a tumor suppressor because it negatively regulates multiple oncogenes such as Src, BCR/ABL, and survivin." (PMID 26847520, 2016). "The idiotype determinants of the immunoglobulin B-cell Receptor (Ig-BCR) of B cell malignancies are unique for a given clonal population and function as specific tumor antigen that may be exploited for targeted therapies." (PMID 25983658, 2015). "Discovery strategies aimed to identify novel driver oncogenic lesions have succeeded in enrichment of the catalog of therapeutic targets, the most striking of which is BCR–ABL where TKI therapy has conferred tremendous benefits to CML patients with a sustained debulking of tumor burden." (PMID 24747972, 2014). "Additionally, enhanced suppression of apoptosis in tumor cells plays an important role in the process of BCR/ABL-independent imatinib resistance." (PMID 24626299, 2014).
tumor (continued). "In other words, TKI could be tumor suppressive by preventing spontaneous emergence of clones with high BCR-ABL signaling output." (PMID 24500518, 2014). "Genetic, translational and clinical evidence is discussed to suggest that TKI-induced maintenance of low BCR-ABL signaling output may be potently tumor suppressive, because it abrogates oncogenic addiction." (PMID 24500518, 2014). "In CML patients during IM treatment, enhanced Separase proteolytic activity in bcr-abl-positive stem and progenitor cells with residual BCR-ABL protein expression may promote tumor heterogeneity, clonal evolution and development of resistance." (PMID 22870341, 2012). "Indeed, a previous study has shown that IRF4 functions as a tumor suppressor to inhibit BCR/ABL oncogene induced B cell acute lymphoblastic leukemia (B-ALL)." (PMID 21818355, 2011). "Furthermore, emerging evidence indicates that SH3BP5 influences tumor stemness by modulating the BCR and WNT signaling pathways, while its interaction with the JNK axis may contribute to resistance to chemotherapy and immunotherapy." (PMID 40993727, 2025). "Despite associating ERα total protein levels with BCR, proteomics analyses did not distinguish between ERα levels in the different cells from the tumor microenvironment, nor did the analyses distinguish between active (nuclear) or inactive (cytoplasmic) receptors." (PMID 38625747, 2024). "Notably, the HBsAg-positive group exhibited a decreased mutation frequency of CD79B, a key molecule of the BCR pathway; thus, HBV infection may affect the immune escape mechanism of tumor cells and, thus, the mutational selection of CD79B." (PMID 38318173, 2024). "Moreover, the analysis is simple, rapid and useful for early tumor diagnosis; this nanostructured system might be a valid option for the genetic detection of the BCR/ABL fusion gene." (PMID 36612142, 2022). "Moreover, the phage display technology for the identification of peptide ligands for a wide range of receptors could also be used to study BcR IG idiotypes in order to monitor CLL tumor cells." (PMID 35327406, 2022). "However, our study shows that the transfer of the BCR/ABL gene from tumor-derived EVs to neutrophils may promote the invasive and metastatic process in vivo." (PMID 25133686, 2014). "In order to evaluate whether MDSCs belong to the tumor clone or normal residual cells, in 3 patients we analyzed BCR/ABL expression in both CD11b+CD33+CD14-HLADR- and CD14+HLADR- subpopulation cells and all samples showed the oncoprotein expression in both the two subsets (data not shown)." (PMID 25014230, 2014). "Determination of the immunological specificity of the hallmark monoclonal IgM protein may lead to additional insights into the natural history of WM, because it may reveal the underlying antigens that stimulated WM precursors by virtue of BCR signaling in the course of tumor development." (PMID 24106612, 2013). "Our study demonstrate that SESN3 is significantly down-regulated in T-ALL patient samples and acts as a novel tumor-suppressor in T-ALL, which is in line with the fact that SESN3 suppresses the growth of BCR-ABL+leukemic cells." (PMID 41275290, 2025). "The TCA cycle pathway emerged as the most significant at day 21 post-BCR::ABL1 induction, consistent with the Warburg effect observed in tumor cells." (PMID 40221405, 2025). "The most potent compound, 10m, demonstrated inhibition of BCR-ABL-dependent signaling and showed an anti-tumor effect against K562 cells, with an IC50 value of 0.98 μM." (PMID 40076290, 2025). "To gain a more profound insight into this question in a clinically relevant context, we aim to collect tumor samples from CML patients, and explore potential correlations between cellular neddylation levels and therapeutic outcomes of BCR::ABL1-targeting TKIs." (PMID 40447744, 2025).
tumor (continued). "By targeting the BCR-ABL tyrosine kinase and other kinases, such as c-KIT and PDGFR, imatinib directly disrupts proliferative signalling pathways critical for tumour cell survival and growth." (PMID 41426918, 2025). "In CD19-targeted CAR T cells, the primary on-target-off-tumor toxicity occurs in the B-lineage tissues due to the expression of CD19, a BCR co-receptor on B cells." (PMID 38962014, 2024). "Lymphocytes with various surface antigens will create diverse functions during tumor growth, implying that different TCR/BCR can take on particular roles." (PMID 37965341, 2023). "In particular, this is of great importance in CML routine BCR::ABL1 monitoring, as the number of BCR::ABL1 cDNA targets is considered to exactly reflect the tumor load." (PMID 37568730, 2023). "Herein, we showed that miR-181a inhibition enhanced the growth of NBM CD34+ cells and that this effect was enhanced by BCR-ABL, which strongly suggested the tumor-suppressor role of miR-181a in BCR-ABL+ leukemic cells." (PMID 38103082, 2023). "Among various constitutively- and BCR/CD40-mediated factors secreted, tumour subsets co-express two important immunoregulatory cytokines, IL10 and TGFβ1, both associated with a memory B cell phenotype." (PMID 36973425, 2023). "Imatinib binds to the amino acids of the BCR/ABL tyrosine kinase ATP-binding site to prevent tyrosine autophosphorylation, which contributes to influence tumor growth." (PMID 37047794, 2023). "Different TCR/BCR libraries should be evaluated in order to comprehend the individual roles of T cells and B cells in tumor occurrence and progression, and then the technique of integrating TCR/BCR sequencing with single-cell sequencing has evolved." (PMID 37965341, 2023). "CLL tumour cells receive supportive microenvironmental signals, such as BCR ligation, IL-4 and CD40L, within the lymph nodes of patients, promoting tumour cell survival, proliferation and drug resistance." (PMID 37528310, 2023). "This study aimed to finely characterize the dynamic tumour immune contexture of human EBV (+) GC treated with immunochemotherapy by longitudinal scRNA-seq and paired scTCR/BCR-seq." (PMID 37735150, 2023). "RNA-seq analysis demonstrated that tumor cells recapitulate hallmarks of MCL-LN (proliferation, NF-kB and BCR), with T cells exhibiting an exhaustion profile (PD1, TIM-3 and TIGIT)." (PMID 37031299, 2023). "Currently, downstream BCR signaling molecules (PKD2 or BTK), tumor cell-derived IL-18 cytokine, and Breg-cell-mediated IL-35 are utilized to target pro-tumorigenic suppressor B cells in PDAC." (PMID 37033931, 2023). "We observed that all CRISPR/Cas treatment modalities targeting the BCR/ABL1 fusion gene were beneficial with respect to the tumor volume, as assessed 30 days post tumor electroporation." (PMID 35739111, 2022). "Significant correlations were observed between the expression of DDR1, EGFR, and SRC/BCR axis, indicating its active involvement in COAD [source: GEPIA; datasets, TCGA (tumor), GTEx (Normal)]." (PMID 35664781, 2022). "We here investigated the combination of different TKI and blinatumomab in BCR::ABL1+ and BCR::ABL1− B-ALL cell lines and primary samples regarding T cell proliferation, differentiation, cytokine release and killing of tumor cells." (PMID 35551463, 2022). "We found that anti-tumor immunity pathways, including cytokine production, chemokine signaling, TCR signaling, BCR signaling, and negative regulation of lymphocyte apoptosis, were significantly downregulated in the high-ADI group." (PMID 35634419, 2022). "Consistent with the previously reported tumour-suppressor role of PP2A, its activating drugs, such as FTY720 and OP449, have been shown to re-sensitize TKI-resistant LSCs to BCR::ABL1 inhibition by targeting the JAK2/PP2A/β-catenin pathway." (PMID 35884363, 2022). "Dasatinib, a different TKI, can block the activities of the ATP-binding site of BCR/ABL, provoking programmed cell death of CML cells and inhibiting tumor cell growth." (PMID 36612142, 2022).
tumor (continued). "We determined that three oncogenes, PD-L2, ETV5, and MTOR and 113 long intergenic non-coding RNAs (lincRNAs) were constantly up-regulated, whereas two oncogenes, BCR and GTF2I, one tumor suppression gene MEN1, and 30 lincRNAs were constantly down-regulated." (PMID 35317849, 2022). "Subcutaneous injection of these BCR/ABL-trapped cells into immunodeficient mice led to a strong inhibition of tumour growth, resulting in a 90% reduction in tumour burden relative to control tumours (Cas9 + donor and parental), 23 days post-injection." (PMID 35742831, 2022). "We cannot discard a direct interaction among LINC00173 and BCR/ABL1 in BCP-ALL, since it is widely known that certain proteins involved in cancer favor tumor progression through modulation of lncRNA expression." (PMID 35719952, 2022). "The effective activation of anti-tumour response also relied on the recognition of neoantigens by TCR and BCR repertoires." (PMID 35999267, 2022). "The effects of the constitutive BCR/ABL activity are pleiotropic and promote leukaemogenesis by acquisition of tumour abilities." (PMID 35742831, 2022). "The IL-7-mediated JAK1/STAT5 pathway bypasses BCR/ABL signals, protecting tumor cells from imatinib (IM) and nilotinib (NI) in a BCR/ABL-independent way." (PMID 34095111, 2021). "Furthermore, we found a set of BCR light chain variable region genes expressed differentially in the tumor region, which should help to gain deeper insight into the humoral immunity and the relationship between gastrointestinal microbiota and tumor progress for CRC." (PMID 33463049, 2021). "This circRNA promotes CML progression by acting as a sponge for miR-29b, which plays a tumor-suppressive role by targeting both ABL proto-oncogene 1 (ABL1) and breakpoint cluster region protein–ABL (BCR-ABL) protein expression." (PMID 34747369, 2021). "In this study, we conducted the first comprehensive characterization of TCR (α, β, γ, and δ chains) and BCR (IgL, IgK, and IgH) CDR3 from the bulk RNA-seq data from both pediatric and adult AML samples as well as non-tumor controls." (PMID 31771646, 2019). "TRUST derived a total of 1,210,000 BCR (IgL, IgK, and IgH) CDR3s from the AML and non-tumor samples." (PMID 31771646, 2019). "In this study, we systematically analyzed the T cell receptor and B cell receptor (TCR and BCR) repertoires from the RNA-seq data of 145 pediatric and 151 adult AML samples as well as 73 non-tumor peripheral blood samples." (PMID 31771646, 2019). "In the present case, a chromosome 22 aberration and BCR-ABL gene expression were confirmed by fluorescence in situ hybridization (FISH), thereby verifying that PN is a tumorous disease." (PMID 30213264, 2018). "This conforms with our second finding, that once the first phase of the typically bi-phasic BCR-ABL decline has been completed, the average velocity of further tumor load reduction does only marginally differ between the two TKIs." (PMID 30120281, 2018). "The effects of the constitutive BCR/ABL activity are pleiotropic and promote leukemogenesis by acquisition of tumor abilities." (PMID 28212528, 2017). "The serine/threonine phosphatase 2A (PP2A) functions as a tumor suppression by activating protein tyrosine phosphates 1 (SHP-1), which catalyzes BCR/ABL dephosphorylation and proteosomal degradation." (PMID 27999193, 2017). "Both wild-type and mutant forms of BCR-ABL can be efficiently degraded by oridonin, supporting its efficacy observed in cultured cells as well as mouse tumor xenograft assays with either imatinib-sensitive or -resistant cells." (PMID 28128329, 2017).
tumor (continued). "Nonetheless, the mechanisms by which tumor antigens alter the behaviors of T and B cells and TCR/BCR sequences play function in tumor immunology need to be unresolved." (PMID 28881849, 2017). "All together, these data indicate that DOK proteins act as tumor suppressors through the inhibition of the RAS-MEK-ERK pathway, but in CML their function is directly inhibited by BCR-ABL." (PMID 27184141, 2016). "Although tyrosine-kinase activity of BCR/ABL is essential for CML pathogenesis, additional BCR/ABL functions along with hematopoietic stem/progenitor cells and tumour microenvironment biology are likely to contribute to the disease development and maintenance." (PMID 26682280, 2015). "Re-expression of this microRNA has been shown to significantly reduce BCR-ABL fusion protein levels and to coincidently inhibit tumor cell proliferation." (PMID 26177635, 2015). "The chimeric p210 BCR-ABL fusion protein, comprising products of either the b2a2 or b3a2 exon junction, represents a potentially immunogenic tumor-specific antigen." (PMID 23241263, 2012). "Tumor-associated translocations in peripheral lymphocytes may be transitory since sequential blood samples were not always positive for gene fusions, as shown for the BCR/ABL hybrid gene." (PMID 21637673, 2009). "Inhibition of BCR-ABL using the specific kinase inhibitor imatinib (Gleevec) results in cell death and tumor regression." (PMID 17973573, 2007). "In blast crisis, increased expression of the BCR/ABL oncoprotein accounts for the block of differentiation, inactivation of factors with tumour suppressor activity and decreased genomic stability of the Ph1 blasts." (PMID 16953242, 2006). "Our study is based on heterogeneous, non-edited and immune-naïve mouse BCR/ABLp185+ B-ALL tumour cell lines, which were co-cultured for several weeks with mouse NK cells." (PMID 39642167, 2025). "A frameshift alteration detected in the BCR gene in MC-LMP and no VHL gene mutation compared to ccRCC suggests likely separate clonal evolutionary mechanisms, despite the two neoplasms sharing overlapping histomorphology." (PMID 40860802, 2025). "The BCR::ABL1 (BCR—breakpoint cluster region; ABL1—ABL protooncogene 1) translocation is one of the most extensively studied abnormalities in tumor cytogenetics, resulting in the iconic Philadelphia chromosome (Ph-chromosome), which is a shortened version of chromosome 22." (PMID 39846605, 2025). "Even though the function of this protein is still not clearly defined, it is thought to be related to BCR function as a lymphocyte-specific tumor suppressor." (PMID 39035000, 2024). "First, we observed a dramatic reduction in the transitions of the same BCR clonotypes between GC B and plasma cells in the NPC tumours at the advanced stages compared with that at the early stages, suggesting that neonatal plasma cells through GC reaction were decreased in the advanced tumours." (PMID 39231979, 2024). "For instance, an important observation is that no PCa metastasis and no BCR cases among RTRs were detailed, arguing against a greater likelihood of (immunosuppression-related) tumour progression in RTRs, which was previously reported." (PMID 36710292, 2023). "Interestingly, LCK showed a similar pattern of upregulation in DLBCL tumor samples as BTK and SYK, both of which drive the BCR signaling pathway and are therapeutic targets in B-cell malignancies." (PMID 36711753, 2023). "Moreover, the dual inhibition of BCR::ABL1 and FLT3 via combined treatment of imatinib with quizartinib further impaired tumor growth." (PMID 37932786, 2023). "Our efforts have resulted in effective degradation of BCR–ABL protein by the N-end rule pathway and efficient growth inhibition of K562 cells expressing BCR–ABL in vitro and blunted tumor growth in a K562 xenograft tumor model in vivo." (PMID 37392851, 2023).